TBRG1 (transforming growth factor beta regulator 1)
Description:
Acts as a growth inhibitor. Redistributes CDKN2A into the nucleoplasm. Involved in maintaining chromosomal stability.
Synonyms: NIAM; FLJ14621; TB-5
Tractability: PROTAC: UniProt records ubiquitination sites on it.
Gene: Protein-coding gene on chromosome 11 (124,622,836 to 124,635,926, forward strand). Ensembl gene ENSG00000154144.
Subcellular location: Nucleus
Subcellular location (Human Protein Atlas): Nucleoplasm
Gene Ontology:
Molecular function: protein binding
Biological process: DNA replication; negative regulation of cell population proliferation; protein localization to nucleoplasm; protein stabilization; regulation of cell cycle
Cellular component: nucleoplasm; nucleus
Genetic constraint (gnomAD): Loss-of-function variants: 26 observed, 32.88 expected, observed/expected ratio (o/e) 0.79, 90% interval 0.58 to 1.1. The upper end of that interval is the gene's LOEUF score, 1.1, which puts it in group 4 of 6, group 1 being the genes least tolerant of losing a copy. Missense variants: 439 observed, 441.59 expected, observed/expected ratio (o/e) 0.99, 90% interval 0.92 to 1.08. Synonymous variants: 160 observed, 174.67 expected, observed/expected ratio (o/e) 0.92, 90% interval 0.81 to 1.04.
Homologues: Orthologues: chimpanzee TBRG1 (99% identical), macaque TBRG1 (98% identical), pig TBRG1 (90% identical), guinea pig TBRG1 (86% identical), mouse Tbrg1 (84% identical), rat Tbrg1 (84% identical), rat LOC100911055 (83% identical), dog TBRG1 (81% identical), rabbit TBRG1 (76% identical), tropical clawed frog tbrg1 (58% identical), zebrafish tbrg1 (52% identical), Drosophila melanogaster CG31111 (22% identical).
Diseases named in the same sentence as TBRG1 in open-access papers:
TBRG1 is named in the same sentence as 16 diseases in open-access papers, as found by Europe PMC text mining. Sharing a sentence is not in itself a finding about the gene and the disease. The quoted sentences say what the papers report.
B-cell lymphomas (4 papers, 2014 to 2022). "Inhibition of miR-155 target gene TBRG1 expression by overexpression of miR-155 increased cell proliferation in B-cell lymphomas." (PMID 35602303, 2022).
breast cancer (3 papers, 2014 to 2020). A primary or metastatic malignant neoplasm involving the breast. "Recent RNA sequencing data from The Cancer Genome Atlas (TCGA) project is now available for certain cancers and verifies that there is a marked decrease in NIAM (gene name Tbrg1) mRNA levels in human lung, liver, bladder, and breast cancers as compared to paired, normal tissues." (PMID 25393878, 2014). "MiR-874 was experimentally shown to repress TBRG1 to promote non-familial breast cancer." (PMID 32411683, 2020).
osteosarcoma (1 paper, 2022). A usually aggressive malignant bone-forming mesenchymal neoplasm, predominantly affecting adolescents and young adults. "The three genes (COL13A1, MXI1, and TBRG1) regulated by DNA methylation were identified to relate with the outcomes of OS patients, which might provide a new insight to the pathological mechanism of osteosarcoma." (PMID 35602303, 2022). "In addition, effects of DNA methylation inhibitors on osteosarcoma cell phenotype and prognosis in animal models targeting the three identified genes (COL13A1, MXI1, and TBRG1) deserve further study." (PMID 35602303, 2022).
ovarian carcinoma (1 paper, 2012). A malignant neoplasm originating from the surface ovarian epithelium.
tumor (10 papers, 2014 to 2024). "Transforming growth factor beta regulator 1 (TBRG1) acts as a growth inhibitor and tumor suppressor." (PMID 35602303, 2022). "With 3′US in ER- tumor samples, TBRG1 is significantly down-regulated (log fold change = −0.15) considering the general up-regulation of the other housekeeping genes." (PMID 32411683, 2020). "Although miR-874 was expressed (average FPM is 5.3 and 5.1 in ER- tumor and normal samples), they were not significantly (P = 0.58) up-regulated in ER- tumor samples to repress TBRG1." (PMID 32411683, 2020).
cancer (8 papers, 2014 to 2025). A tumor composed of atypical neoplastic, often pleomorphic cells that invade other tissues. "MAG1, FYN, and TBRG1 have been investigated in the context of cancer and cellular migration, which may provide insights into immune cell dynamics and the regulation of inflammatory pathways." (PMID 40141401, 2025). "First, TBRG1, PICH1, NBL1, TRIM13 and APC did not impact gene up-expression in cancer." (PMID 33580150, 2021). "Indeed, except for that PTCH1, KLK10, TBRG1, NBL1 and EXT1 did not act on gene expression in stage-2 cancer, the other 21 TS gene had larger positive network effects on gene expression than negative network effects in cancer." (PMID 33580150, 2021).
TBRG1 also shares sentences with these, for which no sentence is quoted: geleophysic dysplasia (4 papers); acromelic dysplasia (2); Acromicric dysplasia (2); lymphoma (2); benign tumors (1); invasive breast carcinoma (1); Marfan syndrome (1); scleroderma (1); stiff skin syndrome (1); Weill-Marchesani syndrome (1).